LINC01762 (long independently transcribed non-coding RNA 1762)
Gene: Long non-coding RNA gene on chromosome 1 (116,423,724 to 116,478,842, reverse strand). Ensembl gene ENSG00000233154.
Diseases named in the same sentence as LINC01762 in open-access papers:
LINC01762 is named in the same sentence as 3 diseases in open-access papers, as found by Europe PMC text mining. Sharing a sentence is not in itself a finding about the gene and the disease. The quoted sentences say what the papers report.
colon adenocarcinoma (1 paper, 2023). "In addition, NSMCE1-DT, AL031985.3 and LINC01762 were reported to be involved in the prognosis of colon adenocarcinoma, hepatocellular carcinoma and renal cell carcinoma, respectively." (PMID 36836069, 2023).
LINC01762 also shares sentences with these, for which no sentence is quoted: hepatocellular carcinoma (1 paper); renal cell carcinoma (1).